ENSG00000267552 (novel transcript)
Gene: Protein-coding gene on chromosome 19 (37,689,865 to 37,719,188, reverse strand). Ensembl gene ENSG00000267552.
Genetic constraint (gnomAD): Missense variants: 116 observed, 138.85 expected, observed/expected ratio (o/e) 0.84, 90% interval 0.72 to 0.98. Synonymous variants: 53 observed, 47.1 expected, observed/expected ratio (o/e) 1.13, 90% interval 0.9 to 1.41.